INS (insulin)
Diseases named in the same sentence as INS in open-access papers (continued):
Sharing a sentence is not in itself a finding about the gene and the disease.
Insulin resistance (continued). "In fact, the significant negative association between changes in trunk fat % and the changes in fasting serum insulin in men was somewhat surprising given that previous studies have shown the markers of insulin resistance (HOMA-IR) is in fact positively associated with visceral/abdominal fat." (PMID 35548564, 2022). "PCOS was often associated with insulin resistance and defects in insulin secretion." (PMID 35418943, 2022). "Loss of insulin signaling in liver cells can lead to severe insulin resistance." (PMID 35269888, 2022). "In addition, comparable insulin resistance in the muscle and liver has been observed following lipid challenges in men and women indicating that the underlying pathology in relation to insulin sensitivity and glucose turnover is comparable between genders." (PMID 36589629, 2022). "Pro-inflammatory cytokines such as CRP, interleukin-6 (IL-6) and tumour necrosis factor alpha (TNF-α) are derived from immune cells or adipocytes and are implicated in inhibiting the insulin signalling cascade whilst also positively associated with insulin resistance." (PMID 36145067, 2022). "Studies have shown that AD and T2DM share many common pathophysiological mechanisms associated with insulin resistance, such as oxidative stress, insulin signaling disorder, mitochondrial dysfunction, neuroinflammation, advanced glycosylation end products (AGEs) and metabolic syndrome." (PMID 35269827, 2022). "The positive association between fetuin-A and insulin resistance is supported by epidemiologic studies and in mice, injection of recombinant fetuin-A decreases insulin sensitivity, Ahsg−/− mice are insulin-sensitive and resistant to weight gain when fed a high-fat diet." (PMID 34998417, 2022). "Considering metformin’s insulin-sensitizing properties, it would be reasonable to suggest that metformin may play a beneficial role in dementia, associated with insulin resistance." (PMID 35615716, 2022). "Hyperglycemia is mainly caused by insufficient insulin secretion or insulin resistance." (PMID 36364943, 2022). "On the other hand, a prospective cohort study revealed that a pattern characterized as energy-dense, high in fat, and poor in fiber could be linked to cardiometabolic abnormalities such as elevated insulin levels and insulin resistance." (PMID 36043034, 2022). "However, we previously demonstrated that impaired insulin secretion rater than insulin resistance underlies the development of Western diet-induced type 2 diabetes in Apoe−/− mouse strains." (PMID 36078077, 2022). "Moreover, hiPSC-CMs developed some key features of insulin resistance upon HP or 3HB culturing, i.e., increased basal FA uptake and loss of insulin-stimulated FA and glucose uptake, as well as loss of insulin-stimulated Akt and S6 phosphorylation." (PMID 36361698, 2022). "However, for T2DM patients, metabolic disorder results in lower insulin sensitivity, insulin resistance, and relative insulin deficiency." (PMID 35056765, 2022). "Overall, abnormal insulin signaling, through a combined effect on both insulin resistance and deficient insulin secretion, becomes a key factor in the pathogenesis of type 2 diabetes, atherogenic dyslipidemia, metabolic syndrome and all related metabolic and cardiovascular abnormalities." (PMID 35055114, 2022). "Insulin resistance causes loss of muscle tissue, which in turn decreases insulin sensitivity if the glucose supply remains constant and, thus, may lead to a vicious circle and the onset of sarcopenia." (PMID 35370985, 2022). "If oxidative stress causes IR cluster dysregulation, then treatment of insulin-sensitive cells with concentrations of an oxidizing agent known to cause oxidative stress might be expected to phenocopy the effects seen with insulin resistance." (PMID 36473871, 2022).
Insulin resistance (continued). "The defective insulin signaling is possibly caused by the increased plasma free fatty acid or decreased mitochondrial β-oxidation levels commonly observed in subjects with insulin resistance." (PMID 36358481, 2022). "The increased insulin secretion observed in prediabetes may be the consequence of an increased insulin demand due to obesity-associated insulin resistance." (PMID 35963866, 2022). "These defects are directly linked with human disorders, such as obesity, insulin resistance, type 2 diabetes, and hyperlipidemia, that induce enlargement of adipose tissue mass and reduce insulin sensitivity, which could cause dysregulation of lipolysis." (PMID 36530555, 2022). "Promoting insulin secretion and increasing insulin sensitivity is a relatively ideal treatment direction for insulin resistance/deficiency lipid metabolism abnormalities, which can effectively accelerate the utilization or storage of FAs to reduce lipid toxicity." (PMID 35509833, 2022). "In humans, insulin resistance is the hallmark of type 2 diabetes mellitus and has been associated with hippocampal hypoconnectivity that can be reversed following administration of intranasal insulin." (PMID 35492025, 2022). "Notably, the depletion of M1 macrophages increases the sensitivity to insulin in obese mice, whereas the reduction of M2 macrophages predisposes to insulin resistance in lean mice." (PMID 35883204, 2022). "Increased levels of insulin are observed in patients with T2DM, which may be due to an increase of endogenous insulin (associated with insulin resistance) or exogenous insulin action (drugs)." (PMID 35299970, 2022). "is positively associated with a higher high-density lipoprotein cholesterol level but negatively associated with fat mass, adipocyte diameter, insulin resistance, levels of leptin and insulin, therefore could be associated with better health." (PMID 36079824, 2022). "This abnormal rise may be caused by a variety of factors, either related to limited insulin production (Type I diabetes) or to deficiency of cell response to insulin, often referred to as ‘insulin resistance’ (Type II diabetes, T2DM)." (PMID 36395096, 2022). "Indeed, chronic supplementation with high doses of antioxidants for control animals has been shown to hinder insulin signalling in liver tissues, and this has been associated with impaired glucose tolerance, insulin resistance and hyperglycaemia." (PMID 35883786, 2022). "It has been suggested that chronic low-level inflammation is one of the most important causes of insulin resistance onset, since chronic exposure to pro-inflammatory cytokines can impair insulin signaling pathways and decrease insulin secretion from beta cells." (PMID 36359548, 2022). "The activation of this pathway promotes insulin resistance, and therefore its downregulation may be associated with improved insulin action." (PMID 36532435, 2022). "This review discusses how NEFA mobilization contributes to the reciprocal relationship between insulin resistance and reduced hepatic insulin clearance, and how this may be implicated in the pathogenesis of non-alcoholic fatty liver disease." (PMID 36009446, 2022). "In addition to impaired glucose control and insulin resistance, pancreatic beta cell loss and impaired insulin, and glucagon production secreted hallmark T2D." (PMID 36077198, 2022). "This condition is caused by defects in insulin secretion and/or insulin resistance." (PMID 35892791, 2022). "A clearer knowledge of the vitamin D molecular contribution associated with insulin signaling may lead to new therapeutic techniques that could help reduce the risk of developing insulin resistance and related conditions." (PMID 35565811, 2022). "Earlier investigations documented that hypocalcemia due to vitamin D deficiency could lead to insulin resistance and impaired insulin secretion." (PMID 35058558, 2022). "Variable combination of insulin resistance and insulin secretory defect/deficiency." (PMID 35800190, 2022).
Insulin resistance (continued). "Moreover, insulin resistance is caused by the inadequate response of insulin in the peripheral tissue, such as adipose, muscle, and liver." (PMID 35669072, 2022). "Some authors hypothesize that these metabolically unhealthy lean subjects could have a lipodystrophy-like phenotype, resulting in a higher risk to develop NAFLD, insulin resistance and impaired insulin secretion." (PMID 35651975, 2022). "Circulating levels of TXB2, the stable metabolite of thromboxane A2, is greater in insulin resistant individuals with obesity, as well as type 1 and 2 diabetes, and has been shown to cause whole body insulin resistance, as well as adipose tissue fibrosis in rodents." (PMID 35980018, 2022). "The mechanism of increase in insulin resistance associated with statin therapy and the cellular mechanisms that could explain the increased insulin secretion are not completely understood." (PMID 36012589, 2022). "Adipose tissue inflammation, a hallmark of obesity and insulin resistance, contributes to aberrant lipolysis in an insulin-independent manner, particularly through the actions of TNFα and other inflammatory cytokines driving obesity-related adipose tissue inflammation." (PMID 35563078, 2022). "This scenario—reduced hepatic insulin clearance, peripheral hyperinsulinemia, insulin resistance and beta-cell stress—could characterize even those at risk for impaired glucose tolerance and type 2 diabetes in the prediabetic state." (PMID 35163746, 2022). "In addition, HOMA-IR mainly reflects hepatic insulin resistance, whereas vitamin D is more associated with insulin-mediated peripheral glucose uptake." (PMID 36313112, 2022). "Increased levels of BCAAs may be a causal factor for developing insulin resistance and T2D by hampering insulin signaling pathways, and the accumulation of toxic BCAA metabolites triggers mitochondrial dysfunction." (PMID 36501195, 2022). "Metformin, an insulin-sensitizing medication, may modify the association between acne vulgaris and insulin resistance (IR)." (PMID 36678524, 2022). "Mg2+ increases insulin-dependent glucose uptake in adipocytes and suggests that Mg2+ deficiency may contribute to insulin resistance in people with T2D." (PMID 36093068, 2022). "All together, there may have synergistic effects of different risk factors on insulin resistance, scientific researchers should cooperate with medical experts to reduce the chances of becoming insulin resistant." (PMID 35794109, 2022). "Visceral obesity could damage the insulin signaling pathway and be associated with insulin resistance, which would cause infectious complications, especially wound infection." (PMID 36034360, 2022). "Insulin tolerance tests are largely a measure of glucose uptake into muscle, and the quadricep muscles had increased intramuscular triacylglycerol, usually associated with insulin resistance." (PMID 35318963, 2022). "The increased inflammatory environment may cause insulin resistance and reduced glucose uptake in insulin-sensitive tissues (muscle and liver), thereby causing glucose intolerance." (PMID 35676248, 2022). "A positive association also emerged with glycemia, insulin levels, and insulin resistance." (PMID 36009775, 2022). "We also discussed how CNS insulin resistance may often be a case of insulin deficiency, where delivery of insulin to the CNS overcomes any signaling deficiencies." (PMID 35884888, 2022). "On the other hand, metabolic dysfunction occurs increasingly with age, including modulation of mitochondrial function, a decline in insulin sensitivity, and alterations in substrate utilization, which are associated with obesity, hyperglycemia, dyslipidemia, and insulin resistance." (PMID 36687675, 2022). "Given our findings on transcripts related to insulin resistance, and that intracellular TAG content is associated with insulin resistance in skeletal muscle, these findings support the overall concept that the KE may improve insulin sensitivity." (PMID 36458175, 2022).
Insulin resistance (continued). "Moreover, they were significantly associated with a decreased insulin secretion/insulin resistance disposition index, which indicated impaired insulin secretory capacity (β = −0.025; p = 7.5 × 10−5)." (PMID 36339414, 2022). "The region-discriminating genus Erysipelatoclostridium was inversely associated with fasting glucose, insulin and insulin resistance in our study, consistent with a previous study showing that Erysipelatoclostridium was positively correlated with the glucose-lowering effects of metformin in humans." (PMID 35357559, 2022). "Type 2 diabetes, obesity (referred to as “diabesity”), and metabolic syndrome associated with increased insulin resistance and/or decreased insulin sensitivity have been implicated with increased oxidative stress and inflammation, mitochondrial dysfunction, and alterations in energy metabolism." (PMID 36531176, 2022). "A longitudinal study that investigated thebidirectional relationship between inflammation and insulin resistance showed that baseline levels of hsCRP and IL-6 (interleukin-6) were positively linked with consequent elevations in fasting insulin, HOMA-IR, and beta-cell function." (PMID 37654824, 2022). "However, when adapting for BMI, the significant association to the measures of insulin sensitivity diminished, suggesting the association of Parasutterella with insulin resistance to be indirectly, mediated via its effect on body weight gain." (PMID 35435797, 2022). "Fontanelli and colleagues have shown that increased consumption of grains, with a total carbohydrates/fibers ratio ≤ 10:1, influences cardiometabolic risk factors (atherogenic dyslipidemia and insulin resistance) by lowering blood triacylglycerols and fasting insulin." (PMID 36185649, 2022). "Genetic predisposition, infections, insulin-resistant drugs, obesity, pancreatitis, and various chronic diseases have been shown to induce insulin resistance; however, the canines included in the present study were healthy with no associated pathology, as determined by blood tests." (PMID 35993079, 2022). "Gut microbiota imbalance may trigger an inflammatory response, and inflammatory factors may cause insulin resistance by affecting the insulin signaling pathway." (PMID 35418976, 2022). "Although unlikely, this may be a confounding influence on the results and could be a cause for insulin resistance occurring in cells incubated with high insulin." (PMID 36548206, 2022). "Moreover, in isolated populations, even higher prevalence rates of loss-of-function mutations in AKT2 and TBC1D4, both involved in insulin signalling and implicated in monogenic insulin resistance, have been described." (PMID 35618782, 2022). "It is already known that CFRD has a large effect on nutritional status and that hyperglycemia, consequent to insulin secretory defects and insulin resistance, could be a causative factor as it has been associated with defective linear growth." (PMID 35358060, 2022). "Therefore, liver insulin signaling is a potential contributor to insulin resistance–associated lipoprotein abnormalities." (PMID 35104242, 2022). "DTG interferences with cellular level insulin signaling and causes defects in lipid metabolism that result in obesity which may lead patients into developing insulin resistance and ultimately increased blood glucose levels." (PMID 35366917, 2022). "It has also been proposed that the PP deficiency itself may contribute to the hepatic insulin resistance, as infusion of PP in one small series improved hepatic insulin sensitivity." (PMID 35558377, 2022). "Finally, FA administration alleviates insulin resistance and inhibits insulin fibrillation associated with T2DM." (PMID 35213966, 2022). "Additionally, CL in BAT was demonstrated to be necessary for whole-body insulin sensitivity, as its loss leads to insulin resistance." (PMID 36671702, 2022).
Insulin resistance (continued). "Furthermore, HOMA-IR (Homeostatic ModelAssessment for Insulin Resistance), plasma insulin levels, and glycated hemoglobin (HbA1c) were also investigated to comprehend the association between insulin resistance and inflammation in T2DM." (PMID 37654824, 2022). "SFAs may increase insulin resistance, where an association between plasma insulin concentration and the risk of BC has been reported." (PMID 36741722, 2022). "Furthermore, vitamin D deficiency is linked to poor diabetic control due to a reported association with increased insulin resistance or a defect in insulin release." (PMID 35345711, 2022). "For example, the insulin signaling via IRs regulates the development of regulatory T cells (Treg); in addition, hyperinsulinemia, which is an insulin resistance hallmark, may lead to Treg function suppression." (PMID 35684149, 2022). "No pharmacologic treatment has been developed to target the pathogenic disturbances observed in skeletal muscle (muscle insulin resistance), although it is responsible for most of the glucose uptake of the entire body under insulin stimulation, and it is considered to be the hallmark of T2D." (PMID 35547584, 2022). "However, the sensitivity of related organs and tissues in diabetic mice to insulin is reduced, and insulin resistance promotes glucose uptake, which causes a variety of biochemical reactions in the body." (PMID 35463673, 2022). "In these studies, the large abdominal fat surface area was associated with an increased risk of insulin resistance, while the small size adipocytes was linked to the body’s insulin sensitivity, although the omental fat remains the only depot that correlates significantly with the metabolic syndrome." (PMID 36232443, 2022). "Notably, defective insulin regulation of glucose transport represents the hallmark of insulin resistance, which is an early pathological feature of type 2 diabetes." (PMID 35057804, 2022). "Microvascular insulin resistance is present in metabolic syndrome and may contribute to increased cardiovascular disease risk and the impaired metabolic response to insulin observed." (PMID 34957859, 2022). "The main objectives of the study are: to determine whether sclerostin is associated with glycemic parameters, serum insulin levels, insulin resistance/ sensitivity, beta-cell function, and adipose tissue insulin resistance (Adipo-IR)." (PMID 36004027, 2022). "Characterized by two main deficiencies; impaired secretion of insulin by β-cells and the inability of insulin-sensitive tissues to respond to insulin (insulin resistance), the pathology of T2D reverts from insulin release and activity that are essential processes for glucose homeostasis." (PMID 36463298, 2022). "At the same time, insulin resistance contributes to atherosclerosis and plaque progression through a variety of mechanisms, including changes in classical cardiovascular disease risk factors and downregulation of insulin signaling pathways." (PMID 35778731, 2022). "If correcting vitamin D deficiency improves insulin sensitivity, it may slow the progression of type 2 diabetes and metabolic syndrome, which includes insulin resistance as a key component." (PMID 36362806, 2022). "Later, ceramide levels in body tissue and plasma were correlated with diminished insulin sensitivity among obese and type 2 diabetic patients; and in 2007, increased endogenous ceramide synthesis came into the spotlight as to cause insulin resistance in vivo." (PMID 35789435, 2022). "However, other blood biomarkers (for example, insulin, homeostasis model of risk assessment-insulin resistance (HOMA-IR), Hemoglobin A1c and C peptide, etc.)should be evaluated to better understand the effects of lycopene on glucose metabolism." (PMID 36615780, 2022).